CD163 (CD163 molecule)
Diseases named in the same sentence as CD163 in open-access papers (continued):
Sharing a sentence is not in itself a finding about the gene and the disease.
tumor (continued). "The result was also confirmed on IL-4-stimulated microglial cells: BV2-derived sEVs were not able to modify the expression of pro-tumor genes (Arg-1, Cd163, Cd206, Fizz-1, and Ym1), with all of them upregulated by IL-4 treatment compared to the control cells." (PMID 34440835, 2021). "We stained primary and recurrent GBM samples for CD163 and observed a higher CD163+ population in the primary tumors than the recurrent tumor samples, in line with our Western blot results (data not shown)." (PMID 34572134, 2021). "Similarly, PIR-B or PD-L1 inhibition reduced the proportion of CD206+ and CD163+ TAMs but elevated that of CD86+ and CD80+ TAMs in tumor tissues with the most obvious alteration in the combined blockade group." (PMID 33537094, 2021). "Additionally, this analysis identified that CD68+ TAMs tend to cluster with tumor cells and away from stromal cells, while CD163+ and CD206+ TAMs tend to cluster with stromal cells and away from tumor cells." (PMID 33882057, 2021). "In the late temozolomide (TMZ) treatment or relapse stage, anti-PD-L1 antibody treatment significantly reduced the infiltration of CD163-positive macrophages into tumors, while a combined PD-L1 antibody and IPI-549 (a Selective PI3Kγ Inhibitor) therapy remarkably inhibited tumor growth." (PMID 34071306, 2021). "The TAM antigens CD68 and CD163 were mainly expressed at the tumour invasive front and stroma, while no expression or only weak expression was observed in tumour nests." (PMID 34884696, 2021). "Since CD163+ TAM have been reported to promote the immunosuppressive microenvironment and cancer progression, we evaluated the potential prognostic impact of PD-1+ helper T cells and CD163+ TAM in tumor cell nests." (PMID 34777389, 2021). "Mirroring this increase in cells expressing M1 markers, the co-culture with SKOV3-R2+ cells opsonized with 3C23K-CHO and murlentamab decreased the proportion of M0 MDMs expressing CD163, CD36 and CD206, three M2 markers involved in TAM tumor promoting and immunosuppressive functions." (PMID 33924378, 2021). "In summary, the present study confirmed that the infiltration of CD68+ TAM and CD163+ M2 TAM had obvious difference in tumor tissue of CC and normal cervical tissue." (PMID 33928349, 2021). "For PFS analysis, residual tumor disease (HR: 1.97, CI: 1.23–3.16, p = 0.005) and the presence of CD68+ CLSs (HR: 2.11, CI: 1.23–3.64, p = 0.007) in model 1 and the presence of CD163+ CLSs (HR: 2.02, CI: 1.17–3.48, p = 0.012) in model 2 were significantly associated with worse PFS." (PMID 34677277, 2021). "We compared the expression level of CD163+ macrophages in tumor tissue of patients without NAC and those who received NAC." (PMID 35237501, 2021). "For panobinostat, the CD163+ macrophage signature was reduced in myeloid cells in all three replicates with FDR<0.05 in two out of three, while the metallothionein signature was increased in both myeloid and tumor cells for all three replicates." (PMID 33975634, 2021). "TAMs are also broken down into subsets based on polarization to the M1 macrophage-like phenotype (pro-inflammatory/anti-tumor) CD68+ CD80/86+ CD11c+ iNOS+ and the M2 macrophage-like phenotype (pro-tumor) CD163+ CD204+ CD206+ Arg1+, with M2-like TAMs being the most immunosuppressive." (PMID 34136405, 2021). "The TME cell population (CD8, CD163 and/or CD68) of the “OSNew” surgical biopsies (n = 17) was analyzed in 287 tumor regions (total of 1260.3 mm2), being morphologically classified into osteolytic (OL, 83.6%, 1118.3 mm2) and osteoid matrix rich (OM, 16.2%, 142.0 mm2) regions." (PMID 33498676, 2021). "Consistently, Foxp3+ cells have been shown to surround CD163+ M2 macrophages, indicating that M2 macrophages stimulated by RANKL/RANK signaling might recruit effector Tregs into the tumor microenvironment of EMPD." (PMID 34436026, 2021). "CD163+ monocytes were highly represented in peripheral blood of all patients, regardless of tumor necrosis." (PMID 33917598, 2021).
tumor (continued). "We also found a significantly higher score for CD11c(+) cells and a lower score for CD163(+) cells in the tumor nest than those in the non-epithelial area of inflamed tissues." (PMID 34407796, 2021). "sEVs treatment did not modify the expression levels of some pro-tumor genes (Cd163, Cd206, and Fizz-1), which were upregulated by gcm treatment." (PMID 34440835, 2021). "Paired paraffin-embedded tumor samples were used to quantify immune cell populations, such as CD11b+ myeloid cells, CD68+ macrophages (Mφs), CD15+ neutrophils, CD8+ T cells, and CD206+, CD204+, CD163+ and CD169+ Mφs, by immunohistochemistry." (PMID 35070979, 2021). "Interestingly, CD163, a commonly used marker of M2 polarized macrophages was significantly higher in spontaneous UPS tumours compared to transplanted UPS tumours (p<0.001, one-way ANOVA with post-hoc Tukey)." (PMID 34242269, 2021). "The large monocyte/macrophage tumour infiltrate is also altered by CHK1i+LDHU treatment, with downregulated expression of CD206 and CD163, markers of classically activated M2 macrophages, and increased expression of iNOS and Msr1, markers of alternatively activated M1 macrophages." (PMID 34359633, 2021). "For the M2 macrophage marker, several CD163-positive (CD163(+)) cells were observed in non-epithelial areas and tumor nests, and many CD163(+) cells were observed in the tumor stroma." (PMID 34407796, 2021). "In contrast, neither CD68+ ov-TAMs, CD163+ ov-TAMs nor the ratio of CD68+/CD163+ ov-TAMs was associated with age, FIGO stage, residual tumor or chemosensitivity." (PMID 34677277, 2021). "Pre-treatment biopsies and post-treatment tumor resections were analyzed by mIF (PerkinElmer Vectra) using an antibody panel that characterized tumor cells (cytokeratin-positive), immune cells (CD3, CD8, CD163, FoxP3), and PD-L1 expression." (PMID 33413574, 2021). "Also, when the number of macrophages was compared according to tumor heterogeneity evaluated by TA, more CD68-, CD163- and CD204-positive macrophages (p = 0.0078, p = 0.0177 and p = 0.0224, respectively) had infiltrated the heterogeneous tumors." (PMID 34244567, 2021). "However, to better reconstitute the heterogeneity of GBM tissue and the tumour microenvironment we would propose to develop cancer cell lines that are BTK+/SOX2+ and BTK−/SOX2+, along with BTK+/CD163+ and BTK−/CD163+ immune cell populations." (PMID 34645618, 2021). "In contrast, CD14 and CD163 expression were not restricted to invading TAMs and were upregulated by tumor microglia." (PMID 34286275, 2021). "Meta-analysis of nine studies (eight from Chinese cohorts and one from USA cohort), including 794 patients, revealed that higher M1(iNOS+ or HLA-DR+)/M2(CD163+) ratio, but not just CD68 or CD163 expression in tumor tissues, was associated with a favorable OS." (PMID 33194645, 2020). "Whereas a high density of CD163+ TAMs in TN was also significantly related to larger tumor size (p = 0.002), however, not in TS (p = 0.634)." (PMID 32607685, 2020). "Out of 90 NPC cases, 87 specimens (96.6%) expressed CD163+ cells, 57 specimens (63.3%) stained ISG15 mainly in tumor cells and infiltrating immune cells, and 49 specimens (54.4%) expressed ISG15+ CD163+ cells, which suspected to be macrophages based on their morphology as well." (PMID 33424843, 2020). "The density of CD163 macrophages was not correlated with the general condition of tumor patients, but with tumor size, tumor differentiation, lymphatic metastasis, depth of invasion and TNM stage." (PMID 32332633, 2020). "While some studies have observed no prognostic role, in others both the number of CD68+ cells and soluble CD163 have correlated to poor overall survival (OS); however, only CD68+ cell counts at the invasive front of the tumour have been found to be independent predictors of reduced survival." (PMID 32843682, 2020).
tumor (continued). "Unlike the expression of PD-L1 and CD163, CD8+ T-cells among tumor and stromal cells in TNBC are associated with a better prognosis and reduced risk of death." (PMID 31937323, 2020). "A peculiar immune profile was found in the GBM08 sample; it was the only one to express PD-1+ cells in periphery of the tumor in association with a high expression of PDL-1 and CD163, while no positivity for PD-1 was found in the TC." (PMID 32899203, 2020). "Selective targeting the TAMs (such as CD163(+) TAMs) rather than pan-depletion demonstrated improved T-cell cytotoxic function tumor regression." (PMID 33363016, 2020). "A case-by-case analysis showed a positive correlation between the stromal CD68 counts and total tumor CD163 counts, but not with the total tumor iNOS counts." (PMID 32824692, 2020). "IHC analysis of 367 primary invasive BC specimens obtained from patients of a Korean cohort without hematogenous metastasis showed that CD163+ macrophages in tumor nest were an independent prognostic marker of reduced OS and DFS." (PMID 33194645, 2020). "The expression levels of CD163 and CD206 in THP-1 cells recovered from co-culture with CHS were quite comparable to those assessed in PMA/IL-4 -treated THP-1, suggesting a tumor-promoted differentiation/polarization towards M2-like macrophages." (PMID 32344648, 2020). "Stromal CD163+ infiltration was significantly associated with the tumor location in the tongue, and stromal and tumoral CD68+ and CD163+-infiltrating TAMs were more abundant in nonsmokers and non-alcohol-drinkers." (PMID 32630659, 2020). "Similarly, stromal and tumoral CD163+ TAM infiltration was consistently and significantly correlated with positive PD-L1 expression (above 10% of tumor cells) (p = 0.01 and p < 0.0001, respectively)." (PMID 32630659, 2020). "Finally, five model parameters were screened out in seven independent tumor-related immune features, including CD8, CD163, FOXP3, PD-L1, and Ki-67." (PMID 33154945, 2020). "In sum, CD163-positive M2-TAMs may suppress the cytotoxic activity and inhibit the recruitment of CD8+ T cells, enabling tumor escape from antitumor immunity." (PMID 32756500, 2020). "Samples from these patients’ tumours were double stained for CD68 and CD163." (PMID 32075091, 2020). "Our results, indicating a prognostic significance of high infiltration of CD68+ and CD163+ macrophages in tumor nest, rather than the total infiltration, highlight the importance of considering the compartmental localization of TAMs in the TME." (PMID 33194593, 2020). "The amounts of TAMs (CD163+ and CD68+) and tumor HA were determined by immunohistochemistry." (PMID 31720917, 2020). "Additionally, the secretion of pleiotrophin by CD163+ TAMs in glioma fostered CSC-mediated tumor growth and the inhibition of this pathway led to decreased tumor growth and prolonged survival in mouse xenografts." (PMID 32117287, 2020). "Interestingly, flow cytometry identified the CD86 and CD163 double-positive TAMs after co-culture with stably transfected CRC cells, indicating that tumor cells induced TAMs of a mixed M1/M2 phenotype." (PMID 32653013, 2020). "Indeed, FOLR2 expression parallels that of CD163 in tissue-resident macrophages, TAM from various tumor types and inflamed synovium." (PMID 32532019, 2020). "We found CD68+, CD163+, and CD206+ TAMs distributed in both tumor stroma and tumor islets." (PMID 32884895, 2020). "In order to localize FPN protein within the tissue, multiplex-immunohistochemistry was applied, combining CD163 as macrophage marker, FPN, and DAPI as nuclear stain, showing enhanced co-localization of CD163 and FPN in tumor tissue compared to adjacent healthy tissue." (PMID 32106629, 2020). "Nevertheless, not much has been established regarding soluble CD163 and its connection to tumor diagnosis." (PMID 33240816, 2020).
tumor (continued). "Based on the founding that tumor suppressor gene ENDOU was negatively correlated with M2 markers of CD163, VSIG4, and MS4A4A, we speculated that ENDOU may also inhibit macrophages M2 polarization in tumor microenvironment." (PMID 33614471, 2020). "The increased infiltration of immunosuppressive CD163+ macrophages, and increased infiltration of regulatory FOXP3+ T cells l, has been shown to favour tumour growth, in contrast to the presence of tumour infilitrating lymphocytes (TILs) which is positively correlated with survival." (PMID 32560564, 2020). "While there was a non-significant correlation with OS, it is possible that this trend is reflective of the increased Breslow depth of tumours with a high number of CD163+ cells, and not an independent negative prognostic effect of the cells themselves." (PMID 32843682, 2020). "By immunohistochemical analysis, in tumor tissue, the median level of CD68+ cells/HPF was 49 (range, 25–87), the median level of CD163+ cells/HPF was 45 (range, 9–104), the median level of CD206+ cells/HPF was 7 (range, 3–37), and the median level of PU.1+ cells/HPF was 58 (range, 12–115)." (PMID 32884895, 2020). "Among the different patients, the immunosuppressive population of M2-like TAMs (CD163+) is the most represented in both the TC and PTA, showing a type of positivity gradient from the periphery to the core of the tumor, suggesting a strong recruitment of these cells to the TC." (PMID 32899203, 2020). "A high density of intratumoural and peritumoural CD163+ macrophages were detected in many tumours; however, this failed to translate into a difference in global gene expression within the tumour tissue." (PMID 32843682, 2020). "Even though there was minimal intra-tumour infiltration of T cells and no detectable expression of PD-L1, high densities of CD163+ TAM were observed." (PMID 33207697, 2020). "Cells exposed to proliferating thyrocytes or Nthy CM had an M0-like phenotype, while cells exposed to senescent thyrocytes or tumor cells CM (STh- and TuC-Macro) showed M2-like polarization (low MHC II, high CD206 or CD163 and high CCL17 production) and displayed tumor promoting activity." (PMID 31113465, 2019). "Higher densities of CD68+CD163+, CD68++CD163+, and CD68+CD206+ macrophages were found within the tumor regions when compared with normal tissues suggesting that these populations were polarized according to their location in the tumor microenvironment." (PMID 31477692, 2019). "In concordance, we previously reported that in rats treated with anti-tumour IgE, tumour-infiltrating rat macrophages did not upregulate the M2 marker CD163." (PMID 30956175, 2019). "IHF results showing F4/80+ macrophages expressed M2-type macrophage markers like arginase 1 (Arg1) and CD163 also confirmed that M2 but not M1-macrophages predominated in the EndoMT cells-promoted tumor masses." (PMID 31847880, 2019). "Intriguingly, we found that CD68 and CD163 were mainly expressed at the tumor invasive front and stroma, with no to weak expression in tumor nest." (PMID 30927925, 2019). "The tumor displayed immunopositivity for CD68, CD163, and a variable Ki-67 proliferation index." (PMID 31906059, 2019). "Above results indicated CD163+ TAMs infiltrated in invasive front may promote the production of MCTC by regulating the EMT process of primary tumor cells, thereby affecting tumor progression and prognosis." (PMID 30927925, 2019). "Since CD163+ TAMs are activated by anti-PD1 antibody, the TAM-related chemokines such as sCD163 and CXCL5 are important to evaluate the recruitment of anti-PD1 antibody in the tumor microenvironment." (PMID 31080803, 2019). "We detected CD163‐positive GAMs mainly in perinecrotic GBM areas, but also in the vital tumor core." (PMID 30506802, 2019).
tumor (continued). "In summary, TAMs may play an important role in promoting tumor growth, invasion and metastasis in TME of DLBCL, and CD163, as considered to be a marker relatively specific to M2 TAMs may serve as a better predictor than the pan-macrophage marker, CD68." (PMID 31694577, 2019). "Here, we observed that high DFO supplementation reduced the CD68 expression without increasing the CD163 expression (M2), despite the increase in apoptotic tumor cell fraction." (PMID 31413815, 2019). "The representative images of FOXP3+Tregs (a) CD163+M2 macrophages (b); the representative positive expression of PD-L1 in tumor tissues (c); the representative negative expression of PD-L1 in tumor tissues (d); CD3+T lympmcytes (e); CD8+T lympmcytes (f)." (PMID 31174544, 2019). "Since stromal ST2 showed inverse correlation with stage and amount of desmoplasia, we evaluated other clinical factors involved in CRC prognosis, such as LN metastasis, tumor budding (TB) and macrophage markers (general marker CD68, M2-marker CD163, and M1-marker iNOS), analyzed by IHC." (PMID 31281317, 2019). "The CD68++CD163+ macrophages (40%) were the next most abundant and the CD68+CD163+CD206+ macrophages remained the abundant population beyond 20 μm from the tumor cell." (PMID 31477692, 2019). "In 14 tumors (across all tumor groups), nuclear staining was present in some large cells that were neuronal specific enolase‐positive, CD163‐negative, and CD45‐negative, and thus likely to be neurons." (PMID 29888503, 2018). "In this context, after 120 h of interaction, CD14+ monocytes/macrophages showed an alternative phenotype (high expression of CD64 and CD163) as well as higher levels of PD-L1 than naïve controls, which did not have any contact with tumour cells." (PMID 30285662, 2018). "Within the tumor core, CD8+ cells are positively correlated with PD-L1 and CD163+ cells." (PMID 30454021, 2018). "High‐level IL‐8 expression in tumor stroma was correlated with high frequent lymph node metastasis, high density of tumor CD68 but not CD163 positive macrophages." (PMID 30311406, 2018). "CD11b+ and CD11c+ pixels were identified at a 240-micron distance, while CD68+ and CD163+ pixels did not exist more than 180 microns away from the tumor." (PMID 30619287, 2018). "What is more, IL‐8 expression level in tumor stroma by immunohistochemical analysis was related to lymph node metastasis, the number of tumor CD68 but not CD163 positive macrophages and patient outcome." (PMID 30311406, 2018). "The incorporation of the infiltration of CD163+ TAMs and CD66b+ TANs into the TNM staging system could more significantly predict the prognosis of GC clinically at certain tumor stage." (PMID 29573574, 2018). "Moreover, to better define PD-L1 protein expression in the immune component (infiltrating or surrounding the tumor), a panel of linage specific antibodies (CD3, CD68, CD20, CD163 CD56, CD57) was utilized, on samples with available material." (PMID 29898687, 2018). "Patient survival was decreased in patients with CD163+ TAMs in TCA (p = 0.041) or TIF (p = 0.021) when compared to patients without these cells in both tumor sites." (PMID 30038715, 2018). "After CM stimulation, the tumor educated macrophages (TEM) decreased the expression of M1 macrophage markers, such as IL-1b, IL-6 and increased the expression of M2 macrophage markers including Arg1 and CD163 compared with M0 macrophage." (PMID 30180849, 2018). "The tumor cells expressed CD68 and CD163, and lysozyme and fascin, when tested." (PMID 30084011, 2018). "In the total cohort, diffuse PD-L1 tumor-cell expression, CD163+ macrophage infiltration, non-classical HLA class I upregulation, and low stromal CD8+ T-cell infiltration were all associated with LNM." (PMID 29942303, 2018).